GPX4 (glutathione peroxidase 4)
Diseases named in the same sentence as GPX4 in open-access papers (continued):
Sharing a sentence is not in itself a finding about the gene and the disease.
cancer (continued). "We proposed a list of described mammalian QRs with reported Km values, the name and structure of the specific inhibitors available for these enzymes, and the IC50 value reported for cancer cells as potential targets to inhibit to promote ferroptosis in conjunction with GPX4 inhibitors." (PMID 33167334, 2020). "Further analysis reveals that the upstream of GPX4 is characterized by lower DNA methylation sites and elevated H3K4me3 and H3K27ac levels, suggesting that a high level of GPX4 in cancer may result from epigenetic regulation." (PMID 33425217, 2020). "However, due to the poor bioavailability of current small-molecule GPX4 inhibitors, the in vivo efficacy of chemical inhibition of GPX4 in cancer models remains to be demonstrated." (PMID 30962421, 2019). "Our study suggests targeting GPX4 as a therapeutic opportunity in CCCs, and highlights that therapeutic approaches can be identified on the basis of cell states manifested by morphological and metabolic features in hard-to-treat cancers." (PMID 30962421, 2019). "As such, the full application of GPx4 inhibitors in cancer therapy remains challenging." (PMID 31527591, 2019). "However, the underlying mechanism is yet to be deciphered, and the full application of GPx4 inhibitors as cancer therapy remains unrealized." (PMID 31527591, 2019). "Gpx4 has been identified as an important regulator of ferroptosis in certain cancer cells." (PMID 29330409, 2018). "But it still could be true that cancer cells will be more sensitive to the inhibition of GPX4 comparing to the normal cells." (PMID 29375387, 2017). "Interestingly, GPX4 has been shown to have a major role in ferroptotic cancer cell death showing that this selenoprotein also plays a role in the malignancy process." (PMID 26569310, 2015). "GPx1 is postulated to prevent initiation of cancer through ROS-mediated DNA damage whereas GPx4 could inhibit growth of established tumors." (PMID 23153283, 2012). "Interestingly, chemoresistant cancer cells markedly overexpress GPX4 and SLC7A11." (PMID 41596341, 2026). "Given the concern that GPX4 inhibitors may have unacceptable toxicity in humans, discovery of combinatorial approaches such as these may be critical to enable the realization of a clinically effective and safe ferroptosis-based drug treatment for cancer." (PMID 41481741, 2026). "Plasma from vitamin E-deficient mice, but not mice fed a control diet, failed to protect GPX4-deficient cancer cells from ferroptosis, and in tumor xenograft models, cancer cells implanted into vitamin E-deficient mice exhibited slower growth than those in control animals." (PMID 40890110, 2025). "Additionally, blocking GPX4 made drug-resistant cancer cells more vulnerable to ferroptosis." (PMID 40552277, 2025). "Recent studies found that Lenvatinib suppresses GPX4 expression, leading to the accumulation of lipid ROS and ferroptosis.[12b] Ferroptosis is a ROS‐dependent form of cell death that may provide new opportunities for cancer treatment." (PMID 40344394, 2025). "DNA methylation and histone acetylation may regulate GPX4 promoter transcription in cancer tissues." (PMID 40191731, 2025). "Treatment of different cancer cell lines, including breast, kidney, and non-small cell lung cancer cells, with high levels of zinc-induced ferroptosis, were marked by an increase in ROS accumulation and lipid peroxidation, a glutathione and GPX4 depletion, and an iron homeostasis alteration." (PMID 40227202, 2025). "Furthermore, GPx4’s dual role in cancer is evident; though it acts as a tumor suppressor by inhibiting ferroptosis in certain cell lines, its overexpression can reduce the efficacy of cancer therapies, such as cisplatin." (PMID 39942544, 2025).
cancer (continued). "Given the widespread overexpression of GPX4 across multiple cancer types, leveraging Cu2+ and erastin to induce autophagy‐dependent GPX4 degradation and thereby sensitize cancer cells to ferroptosis has emerged as a promising therapeutic paradigm that may surpass conventional approaches." (PMID 41323827, 2025). "Furthermore, the expression of GPX4 was closely associated with MHC molecules, immune activation genes, and immunosuppressive genes such as HLA-A, HLA-B, CD160, TNFRSF18, TNFRSF4 and CD276 in most cancer types." (PMID 41142608, 2025). "Hangauer suggested that administering targeted therapy or drug-therapy either before or after GPX4 inhibitor could serve as an alternative approach to enhance therapeutic effect and mitigate toxic side effects, thereby offering a novel method for cancer treatment." (PMID 40855044, 2025). "However, this may also represent a resistance mechanism, as high GPX4 expression is known to protect against oxidative cell death in cancer cells." (PMID 41229446, 2025). "Furthermore, the variable expression of GPX4 in cancers might be attributed in part to the deregulation of GPX4 promoter methylation and gene mutations." (PMID 41142608, 2025). "Therefore, direct targeting and inactivation of GPX4 may be an effective strategy for bypassing adaptive mechanisms and drug resistance in cancer cells." (PMID 40619432, 2025). "In cancer stem cells (CSCs), GPx4 maintains lipid peroxidation homeostasis, sustaining stem cell pluripotency and chemotherapeutic resistance; preclinical studies demonstrate that pharmacological or genetic targeting of GPx4 potently suppresses CSC’s self-renewal capacity." (PMID 40563367, 2025). "However, in a variety of cancer lines, JQ-1 has been reported to promote erastin-induced ferroptosis by downregulating a number of genes associated with this process, such as SLC7A11, SLC3A2, and GPX4." (PMID 40695797, 2025). "Since GPX4 is a key enzyme involved in detoxifying lipid peroxides and suppressing ferroptosis, its overexpression may contribute to resistance to ferroptosis and increased cancer cell survival." (PMID 41229446, 2025). "Therefore, targeting GPX4 in human cancer has been an attractive theme." (PMID 39858464, 2025). "Therefore, Gen induces ferroptosis in cancer cells by downregulating GPX4." (PMID 39668836, 2024). "Moreover, multiple GPX4-independent antioxidant enzymes, such as apoptosis-inducing factor mitochondria-associated 2 (AIFM2, also known as FSP1) and dihydroorotate dehydrogenase (DHODH), inhibit ferroptosis in cancer cells with low GPX4 expression." (PMID 39534872, 2024). "Besides, some researchers believe that GPX4 is closely related to cancer patients' poor prognosis." (PMID 38333875, 2024). "However, NRF2 signaling could be highly context-dependent; for example, GPX4 could be either upregulated or downregulated by NRF2 in different cancer cell lines, making NRF2 a multifaceted modulator of the anti-ferroptotic response." (PMID 38539832, 2024). "Additionally, recent studies suggest that endocrine therapies may increase ferroptosis sensitivity in HR+ cancers by potentially reducing GPX4 activity." (PMID 39867656, 2024). "Moreover, in the cancer field, direct inhibitors of GPX4 expression/activity have been actively searched and many compounds, now called Class-II FINs, have been proposed thus far (e.g., ML162, ML210, FIN56, FINO2, and RSL3), with promising results in vitro and in vivo." (PMID 38539832, 2024). "In these cancer cells, ferroptosis may be induced by regulating factors other than GPX4 and FSP1." (PMID 39594843, 2024).
cancer (continued). "Since the synthesis and expression of GPx4 are regulated by various cellular processes, targeting GPx4 may constitute a promising strategy for the induction of ferroptosis and the promotion of cancer cell death in treatment-resistant cancers." (PMID 38483584, 2024). "While the significance of GPX4 in ferroptosis sensitivity has been established, the ability of GPX4 inhibition to induce ferroptosis is still largely unknown given the range of cancer cell types with varying degrees of inherent resistance across different organ systems." (PMID 39309484, 2024). "Furthermore, sonosynthetic oxygenation suppresses the expression of hypoxia‐inducible factor 1α, leading to reduced stability of downstream SLC7A11 mRNA, which results in glutathione depletion and inactivation of glutathione peroxidase 4, thereby inducing ferroptosis of cancer cells." (PMID 38867396, 2024). "Furthermore, it reportedly operates in parallel with mitochondrial GPX4 and thus could provide a new method for targeted cancer therapy." (PMID 38313306, 2024). "Knockdown or inhibition of DECR1 siRNA might slow the growth of cancer by increasing polyunsaturated fatty acids (PUFAs) and decreasing monounsaturated fatty acids (MUFAs) in prostate cancer cells, thereby inducing ferroptosis in cells by inhibiting GPX4." (PMID 38698113, 2024). "The mesenchymal cell state of cancer cells is generally thought to be related with the spread of metastasis and the acquired drug resistance, and this high mesenchymal cell state has been found to be dependent on the GPX4-mediated lipid peroxidation pathway, which prevents ferroptosis." (PMID 38783959, 2024). "It was reported that inactivation of neurofibromin 2 renders cancer cells susceptible to ferroptosis through inhibiting YAP/TAZ signaling, whereas activation of epidermal growth factor receptor (EGFR) and isocitrate dehydrogenase 1 promote ferroptosis by inhibiting SLC7A11 and GPX4, respectively." (PMID 39568772, 2024). "The study also demonstrated a correlation between PARL or STARD7 expression and cancer cell resistance to the ferroptosis inhibitor protein GPX4, suggesting that targeting PARL or STARD7 could be a potential strategy to disrupt ferroptosis and provide novel approaches for anticancer therapies." (PMID 37548939, 2024). "Indeed, loss of GCH1, 6-pyruvoyl-tetrahydropterin synthase or sepiapterin reductase sensitize cancer cells to GPX4 inhibition and overexpression of GCH1 is sufficient to increase resistance to Gpx4 loss and inhibition and imidazole ketone erastin (IKE) treatment." (PMID 38908072, 2024). "Given this backdrop, the adjunctive use of ferroptosis inducers might offer a therapeutic advantage, particularly as dedifferentiated cancer cell phenotypes, with their accentuated ferroptotic sensitivity, come into focus, where GPX4 emerges as a pivotal mediator." (PMID 38217037, 2024). "Therefore, GPx4 is considered to be a potential cancer therapy target." (PMID 38202704, 2023). "In addition, it has been proven that GPx4 inhibitors play a specific lethal role in persister cells through ferroptosis; therefore, the induction of ferroptosis is a promising method for overcoming the drug resistance of cancer cells." (PMID 37007068, 2023). "Finally, the upregulated GPX4 blocked ferroptosis and promoted cancer progression in ESCC." (PMID 37268653, 2023). "We speculate that the higher iron status of cancer cells compared to normal cells as well as their dependency on GPX4‐protective mechanisms against lipid peroxidation contribute to the selective toxicity of combined GPX4‐suppressing and HO‐1‐inducing compounds toward malignant cells." (PMID 36658724, 2023). "Sensitivity profiling of 177 cancer cell lines to 12 ferroptosis-inducing small molecules (including erastin, RSL3, and their analogs) revealed that diffuse large B-cell lymphomas and renal cell carcinomas are particularly susceptible to ferroptosis through GPX4 inhibition." (PMID 36677534, 2023).
cancer (continued). "In addition, POLD1 knockdown in ccRCC cells significantly decreased the levels of autophagy and ferroptosis signaling pathway-related genes, including p62, NRF2, Keap1 and GPX4, which were reported to serve as the vital regulatory factors in many types of cancers." (PMID 37047824, 2023). "Therefore, Erastin is most likely to be considered as a potential drug for cancer treatment, which also provides new targets and ideas for the treatment of tumors as well.GPX4, as one of the targets of the ferroptosis inducer Erastin, can function by catalyzing the reduction of lipid peroxides." (PMID 37207153, 2023). "Therefore, inducing ferroptosis by small molecules and nanoparticles to inhibit system Xc− and prevent cystine import, inhibit cystine uptake, directly or covalently inhibit GPX4, to induce the degradation or depletion of GPX4, will provide a novel opportunity for the treatment of various cancers." (PMID 36926345, 2023). "Therefore, co-treatment with a GPX4 inhibitor and current standard medications might provide patient benefits by decreasing the number of persistent cancer cells." (PMID 37046995, 2023). "Moreover, in cancer cells treated with GPX4 inhibitors to induce ferroptosis, dihydroorotate dehydrogenase DHODH, a mitochondrial inner membrane enzyme involved in pyrimidine biosynthesis, inhibits ferroptosis by reducing CoQ, suggesting that mitochondrial CoQ reduction inhibits ferroptosis." (PMID 37505079, 2023). "The overexpression of GPX4 may suppress ferroptosis, thus favoring cancer cell survival." (PMID 37626774, 2023). "Furthermore, different thresholds of reactive oxygen species concentration at which cell death occurs may be related to different levels of FSP1 or GPX4 expression in different cancers." (PMID 36576648, 2023). "Therefore, we hypothesize that MCU promotes acetyl-CoA-mediated GPX4 acetylation, which leads to a sustained GPX4 enzymatic activity and consequently protects cancer cells from ferroptosis." (PMID 37502961, 2023). "Therefore, it suggests that SLC7A11 and GPX4 may serve as novel therapeutic targets for cancer therapy." (PMID 37807410, 2023). "The final potential cause for ferroptosis sensitivity may be the increased antioxidant capacity of the cancer cells accompanied by a reduced requirement for pro-survival signaling activities, rendering these cells vulnerable when xCT/GPX4 protection is mitigated." (PMID 36358931, 2022). "However, the genes CDKN2A and GPX4 were highly expressed in cluster A. High expression of GPX4 may inhibit ferroptosis, which in turn promotes the proliferation of cancer cells, resulting in poor prognosis, which is consistent with our findings." (PMID 36132144, 2022). "Therefore, controlling the iron death of cancer cells by inducing GPX4 inactivation might be an effective method for treating cancer." (PMID 35567291, 2022). "However, the molecular mechanism underlying ferroptosis resistance that is mediated by the aberrant activation of GPX4 in advanced cancers, remains unclear." (PMID 35534546, 2022). "In addition, drug-resistant “persister” cancer cells are also highly dependent on GPX4 for survival and this has led to substantial interest in targeting GPX4 to induce ferroptosis as a therapeutic approach in cancer, though GPX4 inhibitors suitable for clinical use have not yet been reported." (PMID 35523770, 2022). "Although GPX4 has played a central role in ferroptosis suppression, the sensitivity toward GPX4 inhibitors varies across a wide range of cancer cell lines, which suggests that other pathways could be related to lipid peroxidation control and, consequently, to prevent ferroptosis in cancer." (PMID 35805884, 2022). "Therefore, it is proposed that iPLA2β is a more promising therapeutic target compared with GPX4 for ferroptosis-targeted therapy in human cancers without causing severe toxicity." (PMID 35882850, 2022). "Therefore, inhibiting GPX4 leads to ferroptosis in cancer cells, thus suppressing metastasis." (PMID 35847022, 2022).
cancer (continued). "In addition to inducing ferroptosis in cancer cells by elevating intracellular ROS levels, numerous studies have demonstrated the effectiveness of cancer-killing by inducing ferroptosis through the inactivation of glutathione peroxidase 4 (GPX4)." (PMID 36551145, 2022). "However, some cancer cells have been proven to survive in response to genetic depletion of GPx4, suggesting that GPx4 suppression alone may be insufficient to kill certain cancer cell types." (PMID 36071041, 2022). "Thus, studying and targeting PTMs of GPX4 has a great potential to treat cancers in the future." (PMID 35647032, 2022). "Moreover, the NPS showed a negative association with GPX4 (an anti-ferroptosis-related molecule) in most cancers except PRAD, TGCT, and LAML." (PMID 36170029, 2022). "Furthermore, GPX4 is a candidate prognostic biomarker for many cancers, so it is necessary to further clarify whether GPX4 is an oncogene." (PMID 35252001, 2022). "We next investigated whether TAK1 is required for cancer-promoting effect of GPX4." (PMID 35105963, 2022). "It is important to find and understand these alternate protective pathways because strategies aimed at promoting ferroptosis in cancer cells via up-regulating GPX4 could potentially be rendered ineffective by the compensatory activation of these other mechanisms." (PMID 35208642, 2022). "Moreover, GPX4 has been identified as a critical survival protein for cancer cells in a high mesenchymal therapy‐resistant cell state in the antilipid peroxidase pathway 14, 23 while there is a paucity of studies investigating the effects of NR2F2 on drug resistance." (PMID 34586745, 2021). "A key finding in this direction is that cancer cells with a more de‐differentiated, mesenchymal phenotype are dependent on GPX4 for their survival and, consequently, more sensitive to ferroptosis triggered by GPX4 inhibition than their more differentiated counterparts." (PMID 34223704, 2021). "Therefore, the development of efficient SDT therapy with simultaneous GPX4 depletion might induce ferroptosis, which incorporates as a highly promising therapeutic approach in cancer therapy." (PMID 33408790, 2021). "Moreover, GPX4 is an important selenoprotein for cellular survival and selenium has been regarded as an essential micronutrient that has a broad influence on human health and disease including cancers." (PMID 34586745, 2021). "Notably, in some therapy-resistant cancer cells with mesenchymal cell-state contexts, inhibition of GPX4 could effectively sensitize cells to ferroptosis." (PMID 37287758, 2021). "Therefore, it’s conceivable that, anti-cancer therapy that targeting GPX4 and/or GSH may bring satisfactory effect." (PMID 33602233, 2021). "The role of xCT in promoting selenium uptake and selenoprotein expression suggested to us that Erastin may also function to disrupt the selenium-dependent expression of GPX4, which given the role of GPX4 in ferroptosis may greatly affect a cancer cell’s sensitivity or resistance to ferroptosis." (PMID 33672555, 2021). "Thus, our findings might have wider implications for our understanding of early events of therapy resistance since GPX4 dependence has been reported in several types of cancer in response to different targeted therapies." (PMID 32577235, 2020). "Besides, GPX4 is a promising target for killing therapy-resistant cancer cells via ferroptosis." (PMID 33425751, 2020). "As our mechanistic data suggests, GPx4 significantly contributes to HCC protection by selenium, even if other selenoproteins as SELP, DIO1 and TXNRD2 show similar positive association with cancer survival and may also be involved." (PMID 29515790, 2018).